NLRP3 (NLR family pyrin domain containing 3)
Diseases named in the same sentence as NLRP3 in open-access papers (continued):
Sharing a sentence is not in itself a finding about the gene and the disease.
ischemic stroke (continued). "Curcumin, sinomenine and chrysophanol can alleviate brain damage and neurological deficits following ischemic stroke while also reducing the formation of the NLRP3 inflammasome and related signaling pathways." (PMID 40075143, 2025). "As expected, TXNIP knockdown reduced the levels of NLRP3, ASC, pro-caspase-1, and IL-1β proteins, indicating that TXNIP’s role in ischemic stroke is associated with the NLRP3 inflammasome pathway." (PMID 39690856, 2025). "In the current article, we preliminarily elucidated that UA inhibits microglia pyroptosis-mediated neuroinflammation after ischemic stroke, at least partly by inhibiting the NF-κB/NLRP3 pathway." (PMID 40717974, 2025). "Among them, the NOD-like receptor protein 3 (NLRP3) inflammasome plays a crucial role in brain injury recovery after an ischemic stroke." (PMID 39753298, 2025). "IL-1β is a key mediator of the inflammatory response following ischemic stroke, primarily produced by activated microglia and infiltrating neutrophils via the NLRP3 inflammasome." (PMID 41451205, 2025). "Recent studies highlight the pivotal role of the NLRP3 inflammasome in post-stroke neurovascular injury, positioning it as a promising therapeutic target in ischemic stroke." (PMID 41408503, 2025). "In ischemic stroke, multiple inflammasomes (NLRC4, NLRP1, NLRP3, NLRP6, AIM2) have been implicated, with AIM2 uniquely recognizing cytosolic dsDNA to drive AIM2-ASC-caspase-1 complex formation and GSDMD-mediated pyroptosis." (PMID 41344159, 2025). "Currently, the most widely studied inflammasome is NLRP3, which mediates the emergence of pyroptosis in various diseases, including dilated cardiomyopathy, ischemic stroke, myocardial ischemia, cerebral hemorrhage, inflammation, and tumors diseases." (PMID 38756773, 2024). "Our data indicated that ChemR23 modulates NLRP3 inflammasome-mediated neuronal pyroptosis in ischemic stroke." (PMID 38178174, 2024). "The improvement of ionic homeostasis, hypoxic conditions, and endoplasmic reticulum stress mediated by BHB collectively leads to the inhibition of the NLRP3 inflammasome, thus reducing neuronal damage by suppressing inflammation during ischemic stroke." (PMID 39075604, 2024). "The NLR family pyrin domain‐containing 3 (NLRP3) inflammasome is the most‐studied type that is activated by ischemic stroke." (PMID 38421089, 2024). "Accordingly, these data indicated that activation of ChemR23 signaling is neural protective against NLRP3 inflammasome-mediated pyroptosis in ischemic stroke." (PMID 38178174, 2024). "Another study using a mouse model of ischemic stroke demonstrated that KD feeding reduced NLRP3 inflammasome activation and ER stress in the brain." (PMID 38198459, 2024). "In conclusion, our results indicate that Cyn possesses neuroprotective properties against ischemic stroke by targeting Alox15, suppressing microglial activation and polarization, downregulating NLRP3-inflammasome components, and mitigating ferroptosis." (PMID 40026597, 2024). "Our previous study revealed that acacetin mitigated ischemic stroke in mouse models by inhibiting microglial overactivation, modulating the NF-κB/NLRP3 pathway, and downregulating inflammatory cytokines such as TNF-α, IL-1β, and IL-6." (PMID 38389927, 2024). "The NLR family pyrin domain containing 3 (NLRP3) inflammasome has emerged as a major contributor to the pathogenesis of ischemic stroke." (PMID 41542272, 2024). "Curcumin ameliorates white matter injury after ischemic stroke by inhibiting microglia/macrophage pyroptosis through NF-κB suppression and NLRP3 inflammasome inhibition." (PMID 38958365, 2024). "The present study found that CMI increases the neuropathology of recurrent ischemic stroke via NLRP3-dependent trained immunity." (PMID 38216560, 2024). "This study planned to mainly evaluate the effects of AS-IV and HSYA on NLRP3 inflammasomes after ischemic stroke and further elucidate the anti-pyroptotic effects via the NLRP3/Caspase-1/GSDMD pathway." (PMID 39199474, 2024).
ischemic stroke (continued). "A study reported that decreasing STAT3 phosphorylation reduced H3 and H4 acetylation on the promoter region of NLRP3 resulting in lower NLRP3 inflammasome expression in ischemic stroke injury." (PMID 38421496, 2024). "Basic research has shown that the combination of aspirin with clopidogrel can alleviate the inflammatory response in ischemic stroke by inhibiting the NF-kB/NLRP3 pathway." (PMID 38377025, 2024). "Consistently, accumulating evidence has shown that NLRP3 inflammasome signaling pathway is involved in ischemic stroke." (PMID 38178174, 2024). "IL-1β and IL-18 antagonists have been shown to inhibit the NLRP3 inflammasome consequently attenuating the adverse effects of ischemic stroke." (PMID 41542272, 2024). "ATP is an important substance for signal communication between microglia and astrocytes, and ATP externalization is a key step in activating the NLRP3 inflammasome to produce inflammatory cytokine IL-1β after ischemic stroke." (PMID 37196132, 2024). "HIF-1α induces NLRP3 inflammasome-dependent pyroptotic and apoptotic cell death following ischemic stroke in adult rats." (PMID 38674050, 2024). "NLRP3 activation plays a pivotal role in ischemic stroke evolution, where mitigating the TXNIP/NLRP3 pathway can diminish oxidative stress and inflammation, thus offering neuroprotection." (PMID 38377025, 2024). "The present study demonstrated that ChemR23 signaling regulates NLRP3 inflammasome-mediated neuronal pyroptosis in ischemic stroke." (PMID 38178174, 2024). "Recent studies have explored potential interventions targeting the NLRP3 inflammasome for neuroprotection in ischemic stroke." (PMID 38601463, 2024). "The specific role of IL‐1 as a downstream product of NLRP3 in ischemic stroke can be found in our review published recently." (PMID 37088947, 2023). "To explore the effects of IPC on NLRP3 inflammasome activation during ischemic stroke, we detected the protein level of NLRP3 components in the penumbra of mice." (PMID 37371374, 2023). "Among the 1584 keywords analyzed in relation to studies on the topic of NLRP3 and ischemic stroke, a total of 222 keywords were identified as having appeared more than 5 times and the co‐occurrence between these 240 keywords was visualized." (PMID 37088947, 2023). "Together, these results indicated early RIC inhibited NLRP3 inflammasome activation after ischemic stroke." (PMID 37580991, 2023). "All these important findings laid an important foundation for subsequent studies related to NLRP3 in the field of ischemic stroke." (PMID 37088947, 2023). "The nucleotide-binding oligomeric domain (NOD)-like receptor protein 3 (NLRP3) inflammasome is believed to be a key mediator of neuroinflammation and subsequent secondary brain injury induced by ischemic stroke." (PMID 37620837, 2023). "Promethazine reduces brain injury after ischemic stroke through PKC-δ/NOX/MnSOD and RIP1-RIP3 regulated activation of the NLRP3 inflammasome following ischemic stroke." (PMID 37483435, 2023). "This study is a scientometric study utilizing quantitative and qualitative methods to comprehensively review the publications on NLRP3 in ischemic stroke." (PMID 37088947, 2023). "Several studies have indicated that ROS generation leads to PARP activation, AIF release, RIPK1 autophosphorylation, RIPK3 recruitment and NLRP3 inflammasome activation in response to ischemic stroke." (PMID 38026442, 2023). "Many studies have shown that NLRP3 plays an important role in inflammatory processes after ischemic stroke." (PMID 36600259, 2023). "The bibliometric analysis provides an objective and quantitative method to assess the trends and leading edge of NLRP3 in ischemic stroke, and provides important insights for researchers to understand the dynamics of the structure and timing of the field." (PMID 37088947, 2023).
ischemic stroke (continued). "In the wake of ischemic stroke, increased DAMPs from injury cells and stimulated NLRP3 protein bind to the adapter protein ASC and pro-caspase-1, subsequently triggering the maturation of precursors IL-1β and IL-18 to induce neuroinflammation." (PMID 37915409, 2023). "In the innate immune system, inflammasomes are the key regulators of neuroinflammatory response in ischemic stroke, such as the nod-like receptor pyrin domain-containing 3 (NLRP3) inflammasome." (PMID 37101593, 2023). "Through bibliometric analysis, the aim of this study was to assess the current state of research on NLRP3 in the field of ischemic stroke research worldwide over the past 12 years and to identify important results, major research areas, and emerging trends." (PMID 37088947, 2023). "The nucleotide‐biding oligomaerization domain (NOD)‐like receptor family pyrin domain‐containing 3 (NLRP3) inflammasome is a multi‐protein complex that plays a role in ischemic stroke." (PMID 37088947, 2023). "This study also summarizes some specific mechanisms by which NLRP3 affects neuronal survival in ischemic stroke." (PMID 37088947, 2023). "To further determine the time course of NLRP3 inflammasome activation and inflammatory reaction, we investigated the changes in NLRP3 inflammasome and inflammatory cytokines at 24 h following ischemic stroke." (PMID 37371374, 2023). "NLRP3 deficiency reduces infarct size, brain edema, and neurological deficits, supporting the role of the NLRP3 inflammasome in ischemic stroke pathogenesis." (PMID 37740008, 2023). "In our previous study done on mice, we found that NLRP3 blockade inhibited neuronal apoptosis and improved neurological outcomes after ischemic stroke." (PMID 38023701, 2023). "Publications related to NLRP3 in ischemic stroke from January 1, 2011 to December 31, 2022 were obtained from the Web of Science Core Collection (WoSCC)." (PMID 37088947, 2023). "Recently, increasing evidence has suggested that the NLRP3 inflammasome play a vital role in detecting cellular damage and mediating neuroinflammation during ischemic stroke." (PMID 37371374, 2023). "Curcumin reduces early brain injury and improves neurological outcomes by suppressing NLRP3 inflammasome after ischemic stroke." (PMID 37915409, 2023). "Research in the role of NLRP3 in ischemic stroke is active and promising, therefore an analysis of the hot spots and trends within the field is warranted." (PMID 37088947, 2023). "The two‐plot overlay of journals displays the distribution of NLRP3 in ischemic stroke research across journal fields and the citation relationships between different journal fields." (PMID 37088947, 2023). "The administration of NLRP3 inhibitor MCC950 decreased infarct volumes to protect BBB integrity in ischemic stroke." (PMID 37915409, 2023). "These two journals publish the most cutting‐edge results and major breakthroughs in NLRP3 research in ischemic stroke." (PMID 37088947, 2023). "A link between early RIC after ischemic stroke with NLRP3 inflammasome was suggested in our current study, and furthermore, investigations are warranted to examine a cause‐and‐effect relationship." (PMID 37580991, 2023). "His most cited paper in this field is a 2013 article published in Cell death & disease that elucidates the inhibition of NLRP1 and NLRP3 inflammasome‐mediated neuronal death in ischemic stroke by intravenous immunoglobulin administration." (PMID 37088947, 2023). "The aim of this study was to perform a bibliometric analysis of research trends and hotspots in NLRP3 in ischemic stroke using the WoSCC database, HistCite Pro 2.1, VOSviewer, R package “bibliometrix”, and Citespace." (PMID 37088947, 2023). "Indobufen, aspirin, and their combinations with clopidogrel or ticagrelor reduced the symptoms of inflammasome-mediated pyroptosis in ischemic stroke by blocking the NF-κB/NLRP3 signaling pathway." (PMID 37033937, 2023).
ischemic stroke (continued). "It has been demonstrated that inhibiting NLRP3 activation can mitigate brain damage and disability after ischemic stroke in a wide variety of rodent models and clinical studies." (PMID 37371374, 2023). "Lately, we have shown an upregulation of NLRP3 and its downstream pro-inflammatory cytokines during the early phases of ischemic stroke (IS)." (PMID 36600259, 2023). "Suppression of the NLRP3 inflammasome pathway is thought to exert neuroprotective effects in ischemic stroke models." (PMID 37088947, 2023). "In this work, we HistCite Pro 2.1, VOSviewer, CiteSpace software, and biblioshiny to analyzed 601 publications on NLRP3 in ischemic stroke using a bibliometric approach and systematically evaluated the status of recent NLRP3 research in ischemic stroke injury." (PMID 37088947, 2023). "NOD-like receptor family pyrin domain-containing 3 (NLRP3) is an important regulator of inflammation after ischemic stroke, with its inhibition being involved in nerve regeneration." (PMID 37915409, 2023). "With the help of HistCite, bibliometrix, CiteSpace, and VOSviewer; we have gained a better understanding of the research developments, hot spots, and future trends of NLRP3 in ischemic stroke over the past 12 years." (PMID 37088947, 2023). "Multiple studies have demonstrated that ischemic stroke leads to the increased expression and activation of the NLRP3 inflammasome in neurons and glial cells, thereby contributing to brain inflammation." (PMID 37681864, 2023). "Research has discovered that the expression of NLRP3 in microglia of patients with ischemic stroke is increased, and the proteins involved in NLRP3 inflammasomes, as well as IL-1β and IL-18, are also expressed at higher levels in the mouse model of MCAO/R." (PMID 36937182, 2023). "ROS production after ischemic stroke can trigger neuronal cell damage, brain edema, and neurological deficits by stimulating the brain inflammatory response and NLRP3 inflammasome." (PMID 37088947, 2023). "His six publications in the field of NLRP3 and ischemic stroke have been cited 894 times, indicating the recognized outstanding contribution of Arumugam TV in this field." (PMID 37088947, 2023). "One of the most relevant authors was Wang J, who published 16 articles related to NLRP3 in the field of ischemic stroke." (PMID 37088947, 2023). "The NLRP3 inflammasome is a crucial component of the innate immune system, playing a role in ischemic stroke." (PMID 37740008, 2023). "The elevation of p-Akt/p-mTOR and the reduction of IL-1β, TLR4, p-38, and p-p38 levels have also been observed after curcumin administration in ischemic stroke and were concomitant with curtailed LC-3-II and NLRP3 markers." (PMID 37915409, 2023). "We addressed the role of the NLR-family pyrin domain-containing protein 3 (NLRP3) inflammasome in the subacute phase of ischemic stroke." (PMID 36600259, 2023). "The inflammatory response following activation of NLRP3 inflammasome plays a significant role in cell death during ischemic stroke and in some pathological conditions, such as SCI, and BHB inhibited NLRP3-associated inflammation." (PMID 36768899, 2023). "Following ischemic stroke, NLRP3 inflammasome was reported to be activated, thus promoting neuron death." (PMID 37101593, 2023). "In conclusion, we identified multiple candidate plasma protein biomarkers of 3-month outcome after ischemic stroke involved in, e.g., NLRP3 inflammasome regulation and signaling pathways, such as TNF, JAK/STAT, MAPK, and NF-κB." (PMID 37794467, 2023). "In summary, autophagy regulators are potential targets for modulating NLRP3 inflammasome in ischemic stroke." (PMID 37915409, 2023).
ischemic stroke (continued). "Pyroptosis, a form of programmed cell death initiated by the generation of the NLRP3 inflammasome, which promotes caspase 1 activation, is involved in the initiation and development of ischemic stroke." (PMID 37681864, 2023). "Arumugam TV, from Australia, is a leader in NLRP3‐related research in the field of ischemic stroke and has a long history of research on immune‐inflammation in the field of neurological diseases such as ischemic stroke." (PMID 37088947, 2023). "Coincidentally, it has been suggested that NEAT1 alleviate ischemic stroke inhibiting NLRP3 mediated via miR-10b-5p/BCL6 axis." (PMID 36941678, 2023). "Growing evidence points to the importance of NLRP3 inflammasome activation in ischemic stroke inflammation." (PMID 36232980, 2022). "In conclusion, further clinical studies should be conducted that deepen the relationship between clinical signs and ischemic stroke symptomatology and the expression levels of NLRP3 inflammasomes, NLRP1, NLRP2, and NLRC4 in damaged brain tissue." (PMID 36297283, 2022). "Previous studies have demonstrated that Dex regulates NLRP3 inflammasome against diverse pathologic conditions, such as osteoarthritis, lung injury and ischemic stroke." (PMID 35955939, 2022). "A number of studies have highlighted the role of the NLRP3 inflammasome, which is fundamental to the innate immune system and contributes to neuronal and glial cell death during ischemic stroke." (PMID 35403328, 2022). "In this study, we aim to investigate the role and mechanisms of NLRP3 inflammasome and pyroptosis in ischemic stroke after PM2.5 exposure." (PMID 35403328, 2022). "Based on the fact that NLRP3 inflammasome is ultimately mainly expressed in neurons after ischemic stroke, drugs that inhibit NLRP3 inflammasome to alleviate cerebral I/R injury and reduce inflammatory response must be studied." (PMID 35600078, 2022). "Recent studies identified a unique inflammatory factor, the NLR family pyrin domain containing 3 (NLRP3) inflammasome, which is an important mediator of cell damage and inflammation after ischemic stroke." (PMID 36013423, 2022). "In an ischemic stroke model, mTrem1 activated the NF-κB signaling pathway and NLRP3 inflammasome via its interaction with SYK in microglia." (PMID 36068612, 2022). "PM2.5 exposure triggers the activation of NLRP3 inflammasome and pyroptosis under ischemic conditions, which was mediated by an increased ROS production after ischemic stroke." (PMID 35403328, 2022). "In this study, we demonstrated that the ischemic stroke-induced activation of NLRP3 was significantly reduced by MFSCE, as so were the downstream targets of cleaved caspase-1 and caspase-11, mature IL-1β, and IL-18." (PMID 35454994, 2022). "As a pivotal component of innate immunity, the nucleotide‐binding oligomerization domain‐like receptor pyrin domain‐containing protein 3 (NLRP3) inflammasome is thought to play a crucial role in the pathophysiology of ischemic stroke." (PMID 35403328, 2022). "A recent study showed that the NLRP3 inflammasome in neurons drives neuroinflammation in ischemic stroke, while blocking NLRP3 protected against ischemia/reperfusion injury by mitigating inflammation and stabilizing the BBB." (PMID 35403328, 2022). "With the involvement of the innate immune system, the activation and expression site of NLRP3 inflammasome act as a critical role in the development of ischemic stroke." (PMID 35600078, 2022). "Herbal medicines especially traditional Chinese medicines have been an essential approach for the recovery of ischemic stroke, identifying natural herbs which ameliorate I/R injury via NLRP3 inflammasome that has prospective value." (PMID 35600078, 2022). "Another study demonstrated that curcumin inhibits microglia/macrophage pyroptosis by inhibiting NF-κB and NLRP3 inflammasome, thereby improving white matter injury in ischemic stroke." (PMID 36818726, 2022).